DMD (dystrophin)
Diseases named in the same sentence as DMD in open-access papers (continued):
Sharing a sentence is not in itself a finding about the gene and the disease.
dystrophinopathy (continued). "Dystrophinopathies are x-linked muscular disorders which emerge from mutations in the Dystrophin gene, including Duchenne and Becker muscular dystrophy, and dilated cardiomyopathy." (PMID 37759719, 2023). "Dystrophinopathies are X-linked recessive muscle disorders caused by mutations in the dystrophin (DMD) gene that include deletions, duplications, and point mutations." (PMID 36672955, 2023). "Dystrophin deficiency has also been described in a few animal species, and few DMD gene variants have been identified in animals." (PMID 36834603, 2023). "Genetic testing in patients with dystrophinopathies allows for an accurate diagnosis and assumes importance when considering the emergence of treatment measures based on DMD variants." (PMID 38002481, 2023). "The loss of the trans-sarcolemmal linkage via the dystrophin/dystroglycan sub-complex is the key trigger of membrane micro-rupturing in dystrophinopathies." (PMID 37509144, 2023). "ES analysis resulted in hemizygosity for a truncation variant of the DMD gene (NM_004006.2):c.3922-2A>G, classified as likely pathogenic in relation to X-linked dystrophinopathies." (PMID 38202188, 2023). "The other two babies with confirmed P/LP variants in the DMD gene, babies 5 and 15, also had a maternal family history of a dystrophinopathy." (PMID 37350320, 2023). "DMD is part of a spectrum of diseases called dystrophinopathies, caused by pathogenic variants in the DMD gene, which codes for the dystrophin protein." (PMID 37350320, 2023). "The purpose of this large single-centre retrospective study was to report the spectrum of DMD gene variants observed in 750 patients from southern Italy with suspicion of dystrophinopathy, in the last 30 years." (PMID 36672955, 2023). "Dystrophinopathies are caused by mutations in DMD gene, which is located on the short arm of the X chromosome at Xp21.1 locus and represents one of the largest genes in humans." (PMID 36672955, 2023). "After dystrophin, a large, mutated, subsarcolemmal, glycosylated protein, deficient in dystrophinopathies, alpha sarcoglycan, 50 DAG protein, first named Adhalin from the Arabic word adhala (muscle), and then the other sarcoglycans were discovered." (PMID 40757565, 2023). "Dystrophinopathies are X‐linked recessive conditions caused by pathogenic variants in the dystrophin (DMD) gene." (PMID 36424846, 2023). "Dystrophinopathies are X-linked recessive progressive neuromuscular disorders caused by mutations in the dystrophin gene." (PMID 36421868, 2022). "A newborn was considered diagnosed with dystrophinopathy when they had elevated CK-MM and a P/LP variant in the DMD gene diagnostic of DMD or BMD." (PMID 36278620, 2022). "DMD and BMD are classified as dystrophinopathies because they are caused by alterations in the dystrophin gene." (PMID 35270040, 2022). "DMD is an X-linked recessive inherited NMD due to the dystrophin gene mutations can lead to partial to complete dystrophin deficiency." (PMID 35842609, 2022). "The accurate genetic counseling of dystrophinopathies relies primarily on the identification of underlying disease-causing DMD variants in the affected patients and the determination of the carrier status in the family." (PMID 36092865, 2022). "In the future, we hope that canine dystrophinopathy models with an in-frame dystrophin mutation will help in the successful development of new exon-skipping drugs." (PMID 35270040, 2022). "The dystrophinopathies are pathologies caused by mutations in the DMD gene that encodes the subsarcolemmal protein dystrophin." (PMID 35690627, 2022). "Dystrophinopathies are characterized by the almost complete loss or abnormal size of the dystrophin protein isoform Dp427-M in skeletal muscles." (PMID 36362832, 2022). "Dystrophinopathies are X-linked recessive inherited disorders resulting from various pathogenic mutations in the dystrophin gene (DMD)." (PMID 36360209, 2022).
dystrophinopathy (continued). "Such ECG changes are well established in human dystrophinopathy, but few studies have been reported in dystrophin-deficient dogs." (PMID 35270040, 2022). "Dystrophinopathies are genetic disorders caused by mutations in the dystrophin gene located on the X chromosome." (PMID 34640386, 2021). "Dystrophinopathies are the most common single gene disorders leading to muscle wasting, due to mutations in DMD gene." (PMID 33939732, 2021). "Dystrophin deficiency in GRMD dogs arises due to a DMD gene mutation that leads to skipping of exon 7 and an out-of-frame transcript with a stop codon in the amino terminal domain." (PMID 33770101, 2021). "A striking feature of dystrophinopathy is the almost complete loss of dystrophin and a drastic reduction in all dystrophin-associated proteins in contractile fibres." (PMID 34553265, 2021). "Secondly, we have performed a thorough characterization of the DMD molecular alterations and, particularly, of the nonsense variants observed in an Argentinian dystrophinopathy cohort." (PMID 34149409, 2021). "Dystrophinopathies are the most common muscular dystrophies caused by mutation of the dystrophin gene." (PMID 33430797, 2021). "Direct therapeutic targeting of dystrophin deficiency is critical, however, hindered by the large size of the dystrophin cDNA and/or stochastic, often extensive genetic changes in DMD gene." (PMID 34091693, 2021). "As a complement to these therapies aiming to restore dystrophin expression, many compounds targeting secondary effects of dystrophin deficiency or looking for alternatives to dystrophin are also under evaluation." (PMID 34521928, 2021). "Dystrophinopathies are caused by X-linked recessive mutations in the dystrophin gene (DMD) (DMD, MIM#300377)." (PMID 34950096, 2021). "In dystrophinopathies, exon deletions in the DMD gene generally result in a loss of the functional ‘full-length’ dystrophin isoform (Dp427)." (PMID 34833031, 2021). "Firstly, the characterization of the mutational spectrum of the DMD gene in an Argentinian dystrophinopathy cohort." (PMID 34149409, 2021). "Dystrophinopathies are caused by mutations in the DMD gene (Xp21) that lead to the loss (DMD) of dystrophin or reduction (BMD) in its production." (PMID 34502539, 2021). "Multiplex ligation-dependent probe amplification (MLPA), a fast and convenient gene testing method, has gained global popularity, but can only detect 70% cases of dystrophinopathies due to different mutation types in the dystrophin gene." (PMID 33430797, 2021). "Dystrophinopathies are a spectrum of X-linked muscular dystrophies caused by mutations in the DMD gene encoding the dystrophin protein, which helps maintain the integrity of muscle membranes." (PMID 33466756, 2021). "Dystrophin replacement strategies are hopeful for addressing upstream dystrophin deficiency; however, all methods to date use semi-functional dystrophin proteins that are likely to trigger downstream pathways." (PMID 33617542, 2021). "We found 363 cases with a nonsense/frameshift mutation in DMD gene from a total of 1497 dystrophinopathy cases in the registry." (PMID 31919629, 2020). "Dystrophinopathies are X-linked genetic diseases due to dystrophin (DMD, OMIM *300377, HGNC ID: 2928) gene variants." (PMID 32424326, 2020). "DMD and BMD are part of a group of disorders called the dystrophinopathies, which are all characterized by mutations in the DMD gene." (PMID 33238405, 2020). "In dystrophinopathy, the almost complete loss of Dp427-M causes a drastic reduction in the members of the dystrophin-associated glycoprotein complex, which in turn triggers sarcolemmal micro-rupturing and calcium-induced proteolytic degradation." (PMID 32916630, 2020). "There have been many dystrophin‐enabled observations that suggested that it is the downstream consequences of dystrophin deficiency that drive the relentless muscle wasting and loss seen in all DMD boys." (PMID 32608079, 2020).
dystrophinopathy (continued). "Dystrophinopathies are a class of inherited X-linked genetic disorders that impair the proper synthesis of dystrophin, a scaffolding protein found in skeletal and cardiac muscle." (PMID 32138751, 2020). "For females in whom there has been no clinical suspicion of dystrophinopathy, again the prior probability of a DMD variant being pathogenic is much lower than in a patient referred with symptoms suggestive of dystrophinopathy." (PMID 32424326, 2020). "Dystrophinopathies are inherited diseases caused by mutations in the dystrophin (DMD) gene for which testing is mandatory for genetic diagnosis, reproductive choices and eligibility for personalized trials." (PMID 32194622, 2020). "Genetic confirmation of a dystrophinopathy is achieved by demonstrating the presence of a clearly pathogenic variant in the DMD gene." (PMID 32424326, 2020). "In this study, we found 14 BMD cases with a nonsense/frameshift mutation-mediated exon skipping, which accounts for 38.6% of 363 cases with a nonsense/frameshift mutation in DMD gene and 0.9% of 1497 dystrophinopathy cases in Japan." (PMID 31919629, 2020). "In a male patient in whom there has been no clinical suspicion of dystrophinopathy, the prior probability of a DMD variant being pathogenic is lower than in a patient referred with classical symptoms of dystrophinopathy and highly elevated serum CK levels." (PMID 32424326, 2020). "Given that DMD mutations lead to dystrophin deficiency, therapies that restore dystrophin expression have been developed to meet clinical needs." (PMID 32717791, 2020). "This review describes the identification of the cause of the disorder in the late 1980s—dystrophin deficiency—and the emerging therapeutics enabled by increased understanding of dystrophin structure and function." (PMID 32608079, 2020). "One of the most frequently used models of dystrophinopathy is the mdx-23 mouse, which represents a naturally occurring mutant with a premature stop codon-inducing mutation in exon 23 of the DMD gene." (PMID 32916630, 2020). "Dystrophin deficiency can be compensated by upregulation of utrophin, an autosomal homologue of dystrophin." (PMID 31998814, 2019). "In dystrophinopathy, DMD gene mutations include deletions of one or more exons (60–70% of cases) and duplications (5–10%)." (PMID 30836656, 2019). "Dystrophin deficiency caused by DMD gene mutations lack sarcolemmal stability against mechanical stress." (PMID 30836656, 2019). "On the other hand, sanger sequencing for detecting small mutations is costly and time-consuming due to the DMD gene length, making muscle biopsy important for diagnosis of dystrophinopathies." (PMID 30833962, 2019). "Deletions are the most frequent mutation type in dystrophinopathy, as they make up ~68% of all DMD mutations." (PMID 30544634, 2018). "Dystrophinopathies are a set of severe and incurable X-linked neuromuscular disorders caused by mutations in the dystrophin gene (DMD)." (PMID 29973226, 2018). "The comparative proteomic study of the dystrophic mdx-4cv mouse model of dystrophinopathy outlined in this report confirms liver abnormalities and identified expression changes in a variety of liver proteins due to dystrophin deficiency." (PMID 30386187, 2018). "Owing to advances in diagnostic methods, global DMD databases are becoming more useful to uncover associations between DMD mutations and their severity in dystrophinopathy." (PMID 30544634, 2018). "Duchenne (DMD) and Becker (BMD) muscular dystrophies, collectively called dystrophinopathies, are X‐linked and caused by mutations in the dystrophin gene." (PMID 30106246, 2018). "This spontaneous canine dystrophinopathy occurred due to a novel mutation in the minor DMD mutation hotspot (between exons 2 through 20)." (PMID 29843823, 2018). "Nonsense mutations in the dystrophin gene are observed in approximately 15% of dystrophinopathy patients." (PMID 29334995, 2018).
dystrophinopathy (continued). "Due to the clinical evidence of dystrophin deficiency, genetic investigations were focused on the region of the DMD gene (CFAX: 26,290,714–28,333,431)." (PMID 29474464, 2018). "The WT2-iPSC line was used to create the DysC-iPSC line by CRISPR/Cas9 targeting of DMD exon 1 to create a 6 bp deletion leading to dystrophin deficiency." (PMID 30410044, 2018). "The classification of canine dystrophinopathies is complicated by the tendency to associate DMD and BMD with severe and mild clinical phenotypes, respectively." (PMID 28526070, 2017). "There is significant variation in the onset, progression, and severity of DCM in these three dystrophinopathies that share mutations of the same dystrophin gene." (PMID 29367543, 2017). "Dystrophinopathies are an X-linked disease caused by mutations in the DMD gene (OMIM 300377) located at Xp21.2." (PMID 28859693, 2017). "Utrophin is homologous with dystrophin and upregulated in dystrophin deficiency, potentially serving as a dystrophin surrogate." (PMID 28028563, 2017). "Becker muscular dystrophy, a less severe dystrophinopathy, is characterized by in-frame DMD gene mutations." (PMID 28028563, 2017). "Dystrophinopathies are a group of X-linked genetic muscle diseases that are caused by mutations in the dystrophin gene which encodes the dystrophin protein." (PMID 27110250, 2016). "Dystrophinopathy is an X-linked disorder caused by mutations in the DMD gene encoding for the sarcolemmal protein dystrophin." (PMID 26066469, 2015). "DMD mutations were detected in 576 unrelated dystrophinopathy families by combining the analysis of exonic copies and the analysis of small mutations." (PMID 26284620, 2015). "Patients with dystrophinopathy have various types of mutations such as missense, nonsense, deletion, insertion, or duplication of the DMD gene cite as." (PMID 26066469, 2015). "Proteomic studies included both gel-based and label-free mass spectrometric surveys of dystrophin-deficient heart muscle from the established mdx animal model of dystrophinopathy." (PMID 24772416, 2014). "Lastly, these studies acknowledged the complexity of the DMD gene and the unclear connection between DMD mutation and pathogenesis of dystrophinopathies." (PMID 24403852, 2013). "The UMD-DMD France national database catalogs mutations of the DMD gene found in (primarily) French patients with dystrophinopathies." (PMID 24403852, 2013). "Precise identification of DMD mutations and their consequences on mRNA and protein expression is essential to provide accurate genetic counseling in dystrophinopathy families and to include patients in mutation suppression therapies." (PMID 23536893, 2013). "In the X-linked muscular dystrophy (mdx) mouse model of dystrophinopathy, different subtypes of skeletal muscles are affected to a varying degree albeit the same single base substitution within exon 23 of the dystrophin gene." (PMID 23828267, 2013). "Becker's Muscular Dystrophy (BMD) is one of the dystrophinopathies caused due to in-frame deletions of the exons of dystrophin gene leading to incomplete translation of its protein product, Dystrophin." (PMID 23841012, 2013). "Summary of DMD point mutations, clinical phenotype and muscle dystrophin immunostaining in 105 dystrophinopathy patients." (PMID 23536893, 2013). "Skin biopsy as a diagnostic tool in dystrophinopathies has been already reported, as dystrophin is expressed at the plasma membrane of arrector pili smooth muscle cells." (PMID 23169061, 2013). "From a total of 344 female carriers of DMD mutations we identified 24 (7%) patients from 23 unrelated families who presented symptoms associated with dystrophinopathy." (PMID 23092449, 2012). "DMD is characterized by dystrophin deficiency caused by mutations in the dystrophin gene, the largest human gene that spans over 2500 kb on the X-chromosome." (PMID 22462762, 2012).
dystrophinopathy (continued). "We evaluated our re-constructed tree using nine disease-causing exons that have been identified in the dystrophin mRNAs of dystrophinopathy patients." (PMID 22462762, 2012). "Dystrophinopathies are a heterogeneous group of disorders caused by mutations in dystrophin (DMD) gene." (PMID 21396098, 2011). "Mutations at the 5' end of the DMD gene can result in dystrophinopathy with substantial cardiac involvement." (PMID 19830234, 2009). "Dystrophinopathies are X-linked recessive disorders caused by loss of function mutations affecting the dystrophin gene." (PMID 19830234, 2009). "Direct therapeutic targeting of dystrophin deficiency is challenged by the need to target large muscle mass, the extreme size of the DMD gene, 90 times larger than average and extensive genetic alterations, with a mutation rate exceeding that of other human genes (1.10−4 vs. 10−5–10−6)." (PMID 41498377, 2026). "In conclusion, the prevalence of symptoms compatible with ASD and OCD among patients with dystrophinopathies is related to the position of the causal variant in DMD and the consequent involvement of cerebral isoforms, indicating an important genotype-phenotype correlation." (PMID 40451248, 2025). "The prevalence of symptoms compatible with ASD (and higher CARS scores) and OCD among patients with dystrophinopathies are related to the position of the causal variant in DMD and the consequent involvement of cerebral isoforms, indicating an important genotype-phenotype correlation." (PMID 40451248, 2025). "The patients had different DMD mutation locations leading to dystrophin deficiency." (PMID 40254293, 2025). "However, in light of the DMD variant identified in three related half siblings and one full sibling, dystrophinopathy is highly likely." (PMID 41300820, 2025). "This dysfunction is directly linked to dystrophin deficiency, as the use of a read‐through compound (capable of bypassing the premature stop codon in the DMD gene) restored dystrophin expression in DMD astrocytes and rescued the glutamate uptake defect, preventing the associated neurotoxicity." (PMID 40913379, 2025). "Pathogenic DMD missense variants are rarely (less than 1%) reported in dystrophinopathies." (PMID 38486238, 2024). "Notably, X chromosomal inversion disrupting the DMD gene was also identified as the underlying genetic cause in some dystrophinopathy patients." (PMID 39767645, 2024). "Taking these clinical aspects into consideration, one might designate individuals suffering from muscular diseases based on pathogenic variants affecting the DMD gene as dystrophinopathy patients." (PMID 39767645, 2024). "In addition, the novel DMD variants identified in our study expand the genetic spectrum of dystrophinopathies." (PMID 38486238, 2024). "Collectively, these data suggest that understanding the role of mitochondrial biogenesis in the context of dystrophinopathy is still incomplete and requires further research, with specific considerations that should be made for the time-point (age), muscle-type, and dystrophin-deficient model." (PMID 39056750, 2024). "While novel therapies have been in development to specifically address defects resulting from dystrophin deficiency, their effectiveness with respect to cardiac function has been limited due to the diverse range of genetic mutations in DMD and the complex risks of each prospective therapy." (PMID 39056750, 2024). "Thousands of mutations in the DMD gene have been found to cause dystrophin deficiency." (PMID 39056750, 2024). "Primary abnormalities in the DMD gene are the underlying cause of dystrophinopathies, a group of progressive muscle-wasting diseases that include the severe Duchenne type of muscular dystrophy in early childhood and the more benign and later-onset Becker’s muscular dystrophy." (PMID 38250815, 2024). "BMD is a dystrophinopathy, typically due to a mutation in the DMD gene." (PMID 39858576, 2024).